NF1 (neurofibromin 1)
Diseases named in the same sentence as NF1 in open-access papers (continued):
Sharing a sentence is not in itself a finding about the gene and the disease.
neurofibroma (523 papers, 2004 to 2026). An intraneural or extraneural neoplasm arising from nerve tissues and neural sheaths. "All data to date shows that NF1 neurofibroma development requires a somatic NF1 pathogenic variant of the other allele in a SC (called “two-hit,” NF1 -/-), consistent with the Knudson tumor two-hit phenomenon." (PMID 41564118, 2026). "Of the 16 cases, 14 were associated with NF1, and 2 were isolated cases of appendiceal neurofibroma." (PMID 41971055, 2026). "Genome-wide studies have not identified highly consistent, driver somatic variants at other loci in neurofibroma SCs, except where the somatic pathogenic variant is a deletion spanning NF1 and surrounding genes." (PMID 41564118, 2026). "The most characteristic feature of the condition NF1 is the neurofibroma, a benign, multi-cellular tumor which initiates when a cell of the Schwann cell lineage gains a somatic pathogenic variant of the other NF1 allele." (PMID 41564118, 2026). "Plexiform neurofibromas (pNF1s) are benign peripheral nerve sheath tumors caused by NF1 loss, leading to dysregulated RAS/mitogen-activated protein kinase (MAPK) signaling." (PMID 42193887, 2026). "NF1, caused by mutations in the NF1 gene, results in the development of neurofibromas and carries a lifetime risk of malignant transformation into peripheral nerve sheath tumors (MPNSTs) between 8% and 13%." (PMID 40427120, 2025). "Preclinical models of NF1 have been developed across three different vertebrate species—zebrafish, mice, and pig—that recapitulate neurofibromas and other tumors associated with NF1 loss." (PMID 41294711, 2025). "The key role of SCs in the development of neurofibromas was also demonstrated by showing that homozygous loss of NF1 in SCs is sufficient to induce tumors in different mouse models." (PMID 40940747, 2025). "In 1987, the National Research Institute of the United States proposed seven diagnostic criteria for NF-1, including skin milky coffee spots, neurofibromas, inguinal freckles, optic gliomas, Lisch nodules, characteristic skeletal change, and family history." (PMID 41170329, 2025). "In neurofibromas originating from precancerous NF1-deficient SC precursors, sensory axon extension to NF1-mutant DRG neurons results in elevated action potential firing relative to wild-type controls, a process mediated by increased expression of collagen 1a2." (PMID 41163091, 2025). "Compatible with this, in SCs, the loss of neurofibromin leads to increased expression of EMT-TFs such as Snail1, Slug, Twist, Zeb1 and Zeb2, both in cultured cells and in NF1-associated neurofibroma samples." (PMID 40037534, 2025). "Tissue samples from neurofibromas and NF1-associated MPNSTs were analysed using microarray profiling, followed by validation with reverse transcription quantitative PCR." (PMID 40843672, 2025). "We report the case of an elderly male with steroid-dependent UC and NF1-associated neurofibromas involving the intestine and omentum, accompanied by histologically confirmed mast cell infiltration." (PMID 41346988, 2025). "Subsequent surgery confirmed the diagnosis of PTC and neurofibromas, with whole exome sequencing identifying a likely pathogenic variant in the NF1 gene." (PMID 40708944, 2025). "It is worth noting that AAV-K55’s tropism is not limited to MPNSTs and neurofibromas, but can be extended to subcutaneously implanted gliomas, such as the NF1-deficient LN229." (PMID 41022755, 2025). "Neurofibromatosis type 1 (NF1) is a genetic disorder caused by mutation of the NF1 gene that is associated with various symptoms, including the formation of benign tumors, called neurofibromas, within nerves." (PMID 39129390, 2025). "A statistical significance was also observed by comparing neurofibromas, NF1-associated MPNST (n = 24, median H-score 95) and sporadic MPNST (n = 8, median H-score 162.5; χ2 = 20.54, df = 2, P < 0.0001)." (PMID 41317405, 2025).
neurofibroma (continued). "Hybrid neurofibromas/schwannomas are associated with NF1, NF2, and schwannomatosis, whereas hybrid schwannomas/perineuriomas occur sporadically." (PMID 40255822, 2025). "Chen and colleagues reported that the activation of Yap in Schwann cells through knockout of Lats1 and Lats2 drove neurofibroma formation in mice when combined with Nf1 loss, which drives MAPK signaling." (PMID 39804140, 2025). "These tumors mostly develop sporadically, but it is known that neurofibromas and schwannomas are associated with neurofibromatosis type 1 (NF1) and neurofibromatosis 2 (NF2), respectively." (PMID 40255822, 2025). "Although benign neurofibromas are the hallmark neoplasms of NF-1, other nerve sheath tumors such as schwannomas can also occur." (PMID 40416267, 2025). "The criteria include neurofibromas, ≥6 café-au-lait macules (CALMs), optic glioma, Lisch nodules, axillary/inguinal freckling, distinctive bony lesions, or a pathogenic NF1 mutation." (PMID 40051696, 2025). "Neurofibromas are benign peripheral nerve sheath tumors, arising from Schwann cells, most commonly associated with NF-1 and are seen in approximately 40-60% of patients." (PMID 40416267, 2025). "This case highlights a rare calvarial manifestation of NF-1 presenting as a large occipital-lambdoid defect linked to plexiform neurofibroma and meningoencephalocele." (PMID 41185817, 2025). "The transgelin expression was significantly upregulated in NF1-associated MPNSTs compared to plexiform neurofibromas, and this overexpression corresponded with hypomethylation in TAGLN regulatory regions." (PMID 40843672, 2025). "Case Series: Three patients with NF1 (aged 13–27 years) presented with symptomatic, inoperable plexiform neurofibromas (PNs) associated with severe neuropathic pain." (PMID 40565537, 2025). "The data are consistent with lack of tovorafenib antitumor activity being reported in granulocytes/erythroids/macrophages/megakaryocytes (GEMM) models of plexiform neurofibroma harboring germline NF1-LOF mutations." (PMID 40111124, 2025). "In NF1 patients, NF1 loss can promote the development of enlarged benign lesions called plexiform neurofibromas (PNFs)." (PMID 40723291, 2025). "NF–1 is characterized by skin manifestations (e.g., café-au-lait spots, neurofibromas), learning difficulties, and predisposition to tumors such as OPGs." (PMID 40867225, 2025). "Older age was (corrected for pathogenic NF1 variant and PN location) significantly associated with plexiform neurofibroma morbidity." (PMID 39796750, 2025). "Plexiform neurofibromas (PNFs), a hallmark manifestation of NF1 loss, are benign nerve and soft tissue tumors that develop in about 20–50% of patients." (PMID 40563570, 2025). "Patients with NF1-associated plexiform neurofibromas have similarly shown response rates around 70% to treatment with single-agent selumetinib and it is now FDA-approved for that indication." (PMID 40007996, 2025). "Selumetinib: Selumetinib, a MEK1/MEK2 inhibitor approved for NF–1-associated plexiform neurofibromas, has demonstrated efficacy in both NF–1-associated and sporadic OPG." (PMID 40867225, 2025). "This case underscores the necessity of sustained access to targeted therapy and highlights the challenges of managing NF1-associated plexiform neurofibromas in resource-limited settings." (PMID 40271285, 2025). "Patients with NF1 carry a higher risk for the development of other RAS pathway-associated tumors (e.g. plexiform neurofibromas) and glial tumors, including brainstem gliomas and diffuse astrocytomas." (PMID 40007996, 2025). "NF1 patients have an increased risk of developing tumors such as peripheral nerve tumors and plexiform neurofibromas when the second allele of NF1 is mutated that often progresses into malignancies." (PMID 40812791, 2025). "Neurofibromas and MPNSTs are associated with the loss of NF1, a tumor suppressor that inhibits Ras/Raf/MEK/ERK signaling." (PMID 38216572, 2024).
neurofibroma (continued). "In contrast, most nonglial cells, including sensory neurons, are wild-type (in somatic mosaic patients or sporadic neurofibroma) or heterozygous for Nf1 mutations (in most individuals with NF1)." (PMID 38258905, 2024). "In NF1 studies, several data showed that IFN-γ treatment or IFN-γ gene transfection directly inhibited the proliferation of NF1-associated MPNSTs or neurofibroma cells." (PMID 39273214, 2024). "Introducing patient-derived NF1 mutations into hiPSCs impairs Schwann cell differentiation, promotes stemness, and fosters neurofibroma formation." (PMID 39217323, 2024). "NF-1 has also been linked to the formation of plexiform neurofibromas from the Schwann cells, leading to the loss of its heterozygosity." (PMID 39205702, 2024). "Characterized by multiple café-au-lait spots, neurofibromas, and Lisch nodules, NF1 is caused by mutations in the NF1 gene located on chromosome 173." (PMID 39359760, 2024). "Minipigs with either of these NF1 mutations exhibit major clinical hallmarks of NF1, including café-au-lait macules (CALMs), OPGs, and neurofibromas." (PMID 39217323, 2024). "All patients were diagnosed with NF1 via assessment of representative NF1 clinical features, including café-au-lait spots, neurofibromas, and NF1 gene mutations." (PMID 39273214, 2024). "The hallmark features of NF1 include multiple café-au-lait spots, neurofibromas, axillary or inguinal freckling, Lisch nodules, and skeletal abnormalities." (PMID 39359760, 2024). "For example, loss of Nf1 enhances inflammatory cytokine expression in cultured SC, and injury-associated inflammation facilitates neurofibroma development in mouse models." (PMID 38458648, 2024). "Previous studies suggested that loss of heterozygosity (LOH) of the NF1 gene in Schwann cells is a key factor in developing neurofibromas." (PMID 39273214, 2024). "These tumors differ from NF-1-associated neurofibromas in origin and presentation; they are rare, often asymptomatic, and likely stem from somatic mutations." (PMID 38706877, 2024). "While NF1-associated neurofibromas harbor the risk of malignant transformation into malignant peripheral nerve sheath tumors (MPNSTs), the malignancy potential for isolated colonic neurofibromas remains uncertain due to their rarity." (PMID 39070511, 2024). "Neurofibromas should be considered indicative of a broader spectrum of disorders resulting from mutations in RASopathies other than NF1." (PMID 39006611, 2024). "NF1 is a genetic disorder caused by a mutation in the NF1 gene that codes for the neurofibromin protein and is characterized by neurofibromas, Lisch nodules, cafe-au-lait spots, and skeletal abnormalities." (PMID 38975364, 2024). "The patient in question fulfilled the diagnostic criteria for NF-1, exhibiting characteristic cafe-au-lait spots and unilateral severe neurofibroma-related gynecomastia." (PMID 39011455, 2024). "Neurofibromas, typically associated with familiar NF1 and NF2, are well-understood, benign, peripheral nerve sheath tumors." (PMID 39070511, 2024). "Neurofibromas are typically multiple lesions associated with neurofibromatosis, generally known as neurofibromatosis type-1 (NF-1) or von Recklinghausen disease (VRD), which induces skin changes and bone deformations." (PMID 38909194, 2024). "In the context of NF1-associated tumors, the majority of the current published mouse models are limited to the recapitulation of rare sub-types of neurofibromas." (PMID 38900740, 2024). "For this experiment, we leveraged mice harboring the germline Arg1809Cys (R1809C) Nf1 missense mutation seen in people with NF1 who lack neurofibromas and brain tumors." (PMID 38308315, 2024). "Lastly, ancillary findings such as the presence of NF1 in a patient can be indicative of neurofibromas, as they are often associated with this genetic condition." (PMID 38816511, 2024).
neurofibroma (continued). "The clinical diagnosis of NF1 is typically based on the presence of multiple café-au-lait spots, freckling in the axillary or inguinal regions, multiple neurofibromas, Lisch nodules, and confirmed NF1 gene mutations in first-degree relatives." (PMID 39811202, 2024). "Key risk factors for MPNST development include the presence of plexiform neurofibromas, prior exposure to radiotherapy, and significant NF1 gene mutations." (PMID 39768355, 2024). "Plexiform neurofibromas most often develop in patients with NF1 after complete loss of neurofibromin, and are thought to be of Schwann cell origin." (PMID 38543265, 2024). "Plexiform Neurofibroma (pNF) is a pathological condition observed at birth in 20–25% NF1 patients that is a result of genetic mutation of the NF1 gene leading to negative regulation of RAS signaling pathways." (PMID 39110684, 2024). "Plexiform neurofibromas (PNFs) are nerve tumors caused by loss of NF1 and dysregulation of RAS-MAPK signaling in Schwann cells." (PMID 38458648, 2024). "Nonetheless, this model system and evidence support the existence of a therapeutic window to use AgNP in the clinical management of NF1-associated plexiform neurofibromas." (PMID 38543265, 2024). "The primary risk factors for developing MPNST rely on existing plexiform neurofibromas (PN), histologically benign tumors, which develop from Schwann cell biallelic NF1 inactivation occurring in nearly 30–50% of NF1 patients." (PMID 39409151, 2024). "The risk of Recurrence: Some lesions associated with NF1, such as plexiform neurofibromas, arachnoid cysts, or brain tumors, tend to recur, as happened with our case." (PMID 39727655, 2024). "Recent studies have confirmed the efficacy of MEK inhibitors in the management of NF-1-associated plexiform neurofibroma and optic pathway glioma." (PMID 39070150, 2024). "Typical tumors in NF1 patients arise due to loss of function of the NF1 gene in Schwann cells of peripheral nerves and are termed neurofibroma." (PMID 38111842, 2023). "Hybrid neurofibroma/schwannoma is the most represented morphology (71%) in schwannomatosis, while hybrid neurofibroma/perineurioma has been reported in association with NF1." (PMID 37046591, 2023). "The “target sign” described as a hypoechoic lesion with a hyperechoic center was seen in three cases of subcutaneous neurofibromas both solitary and associated with NF1." (PMID 38132037, 2023). "Atypical neurofibromas are characterized by CDKN2A/B deletion in addition to NF1 loss, suggesting this is the next step in tumor progression." (PMID 37164978, 2023). "In one patient diagnosed with a NF1 associated neurofibroma of the retroperitoneal region, an intracapsular tumor removal was carried out since no capsular infiltration was encountered." (PMID 36131157, 2023). "Through previous epidemiological and pathological studies, some scholars have found that 40%–80% of CPT patients are NF-1 gene mutation carriers, and there are neurofibroma-like tissues growing and invading in the diseased periosteum." (PMID 36814904, 2023). "Orthopedic surgeons should be aware that neurofibromas in NF-1 have a significant risk of developing MPNSTs." (PMID 38013269, 2023). "We observed variability within Nf1 indels, a gene characteristically mutated in neurofibromas and MPNST development, that correlated with the complexity of the indels detected as well as the mouse background strain." (PMID 37684258, 2023). "Compared to NF1 patients with intragenic mutations, patients with the 17q11.2 microdeletion typically have a higher number of cutaneous and subcutaneous neurofibromas (more than 1000) and earlier onset (prepubertal)." (PMID 36831560, 2023). "In vivo, different neurofibromas, even in the same individual, can carry different somatic NF1 mutations." (PMID 38136356, 2023). "Evidence from genetically engineered mouse models (GEMMs) demonstrated that loss of Nf1 in a spatiotemporal manner during Schwann cell development gives rise to neurofibromas." (PMID 37140985, 2023).
neurofibroma (continued). "NF1 normally down-regulates the ERK pathway by inactivating RAS, and individuals carrying a heterozygous loss of function of NF1 allele develop numerous neurofibroma tumors throughout their lives." (PMID 38038975, 2023). "NF1 mutations were observed in 44% of MPNSTs, 60% of atypical neurofibromas and 18% of benign neurofibromas." (PMID 37164978, 2023). "Sporadic MPNSTs clustered between the benign neurofibromas and the NF1-associated MPNSTs in the two-dimensional PCA." (PMID 37837931, 2023). "The guideline group underlined the need for increased monitoring of NF1 during transition age to screen for plexiform neurofibromas, ANNUBPs and its’ potential transition to MPNSTs in adulthood." (PMID 36684394, 2023). "All sizeable plexiform neurofibromas are thought to result from an early second mutation giving rise to a loss of heterozygosity of the NF1 gene." (PMID 37569527, 2023). "The earliest tested immunotherapy for NF1-associated tumors was imatinib mesylate, a C-Kit receptor tyrosine kinase inhibitor targeting mast-tumor cell signaling, for the treatment of plexiform neurofibromas." (PMID 37345107, 2023). "A phase II trial with mirdametinib, a MEK inhibitor, for adolescents and young adults with NF1-associated plexiform neurofibromas showed a 42% partial response and a significant decrease in pain ratings." (PMID 37232809, 2023). "The examination of PA cephalograms of NF1 patients reveals topographical relationships of a NF1-characteristic tumor (i.e., the plexiform neurofibroma) and associated bone changes in the facial skeleton." (PMID 38111842, 2023). "Our approach with S indices was applied to cell lines derived from plexiform neurofibromas of patients with NF1 gene mutations." (PMID 38136356, 2023). "In the present case, a mutation in the NF1 gene was detected (c.2326-2A>G) in clinically unaffected skin, a peripheral blood sample, and plexiform neurofibroma, which is known to be a pathogenic mutation affecting mRNA splicing." (PMID 37569527, 2023). "Molecular analysis of the NF1 gene revealed a c.2326-2 A>G splice-site mutation in the clinically unaffected skin, peripheral blood sample, and plexiform neurofibroma, which explains the general clinical symptoms." (PMID 37569527, 2023). "The NF1 variant was presumably inherited from his mother, who was also diagnosed with neurofibromas." (PMID 35606766, 2022). "Already in childhood, NF1 patients typically develop neurofibromas within a range from single to thousands which cannot be predicted by the pathogenic germline NF1 variant instead of microdeletion cases." (PMID 34997843, 2022). "In a recent NF1 single-center study, missense variants negatively correlated with neurofibromas while skeletal defects were linked to frameshift variants and whole gene deletions." (PMID 35885913, 2022). "Affected individuals develop neurofibromas, benign tumors driven by NF1 loss in Schwann cells (SCs)." (PMID 36134665, 2022). "NF1 is caused by the mutation of the NF1 gene, and the classic clinical characteristics include café-au-lait macules, skinfold freckling, benign neurofibromas, brain tumors, iris hamartomas, and typical bony lesions." (PMID 35677169, 2022). "Recently, evidence for a more severe phenotype with higher frequency of spinal and deep neurofibromas were reported in association to the presence of missense mutations located in codons 844–848 of the NF1." (PMID 35885913, 2022). "Loss of neurofibromin 1 is a ‘first hit’ and a major driving force in the development of atypical neurofibromas, plexiform neurofibromas, and ultimately, MPNSTs in NF1 patients." (PMID 35887576, 2022). "SCPs or related boundary cap cells can serve as cells-of-origin for neurofibromas, as loss of Nf1 in these cells causes PN formation." (PMID 35311647, 2022).